ASPHD2 (aspartate beta-hydroxylase domain containing 2)
Description:
May function as 2-oxoglutarate-dependent dioxygenase.
Synonyms: FLJ39838
Tractability: Antibody: UniProt predicts a signal peptide or a membrane-spanning region. PROTAC: ubiquitination databases record sites on it; its protein half-life has been measured.
Gene: Protein-coding gene on chromosome 22 (26,428,729 to 26,445,015, forward strand). Ensembl gene ENSG00000128203.
Subcellular location: Membrane
Gene Ontology:
Molecular function: protein binding
Cellular component: membrane
Genetic constraint (gnomAD): Loss-of-function variants: 11 observed, 33.3 expected, observed/expected ratio (o/e) 0.33, 90% interval 0.21 to 0.55. The upper end of that interval is the gene's LOEUF score, 0.55, which puts it in group 2 of 6, group 1 being the genes least tolerant of losing a copy. Missense variants: 373 observed, 520.5 expected, observed/expected ratio (o/e) 0.72, 90% interval 0.66 to 0.78. Synonymous variants: 223 observed, 220.87 expected, observed/expected ratio (o/e) 1.01, 90% interval 0.9 to 1.13.
Homologues: Orthologues: chimpanzee ASPHD2 (100% identical), macaque ASPHD2 (99% identical), dog ASPHD2 (95% identical), pig ASPHD2 (90% identical), mouse Asphd2 (88% identical), rat Asphd2 (87% identical), guinea pig ASPHD2 (86% identical), rabbit ASPHD2 (83% identical), tropical clawed frog asphd2 (78% identical), zebrafish asphd2 (62% identical), Drosophila melanogaster Asph (18% identical), Caenorhabditis elegans K09A9.6 (16% identical). Paralogues in human: ASPHD1 (43% identical), ASPH (23% identical).
Diseases named in the same sentence as ASPHD2 in open-access papers:
ASPHD2 is named in the same sentence as 2 diseases in open-access papers, as found by Europe PMC text mining. Sharing a sentence is not in itself a finding about the gene and the disease. The quoted sentences say what the papers report.
cognitive decline (1 paper, 2024). "Furthermore, additional studies on the link between human brain aging or aging-related cognitive decline and changes in the expression of ASPHD2, BAD, CRTAP, IPW, and ZNF106 which remain elusive, may also be advantageous." (PMID 38428408, 2024).
tuberculosis (1 paper, 2025). A chronic, recurrent infection caused by the bacterium Mycobacterium tuberculosis. "Notably, ASPHD2 expression exhibited a marked decline following one month of anti-tuberculosis treatment (d = −2.08), underscoring its potential utility as a dynamic biomarker for monitoring therapeutic response in tuberculosis." (PMID 40808944, 2025). "Future studies will aim to enlarge the sample pool to encompass tuberculosis (TB) patients and healthy controls from a broader array of geographic regions and ethnic backgrounds, thereby enabling a more comprehensive validation of the involvement of ASPHD2, GK, and GCH1 in the pathogenesis of TB." (PMID 40808944, 2025). "Collectively, these multi-tiered validation data robustly support the involvement of ASPHD2, GCH1, and GK in tuberculosis pathogenesis and immune activation, highlighting their potential as protein-level biomarkers for the assessment of treatment response." (PMID 40808944, 2025).